IGHV3-64D (immunoglobulin heavy variable 3-64D)
Description:
V region of the variable domain of immunoglobulin heavy chains that participates in the antigen recognition. Immunoglobulins, also known as antibodies, are membrane-bound or secreted glycoproteins produced by B lymphocytes. In the recognition phase of humoral immunity, the membrane-bound immunoglobulins serve as receptors which, upon binding of a specific antigen, trigger the clonal expansion and differentiation of B lymphocytes into immunoglobulins-secreting plasma cells. Secreted immunoglobulins mediate the effector phase of humoral immunity, which results in the elimination of bound antigens. The antigen binding site is formed by the variable domain of one heavy chain, together with that of its associated light chain. Thus, each immunoglobulin has two antigen binding sites with remarkable affinity for a particular antigen. The variable domains are assembled by a process called V-(D)-J rearrangement and can then be subjected to somatic hypermutations which, after exposure to antigen and selection, allow affinity maturation for a particular antigen.
Gene: Immunoglobulin variable (V) gene on chromosome 14 (106,088,122 to 106,088,573, reverse strand). Ensembl gene ENSG00000282639.
Subcellular location: Secreted; Cell membrane
Gene Ontology:
Molecular function: antigen binding
Biological process: immunoglobulin mediated immune response
Cellular component: extracellular region; plasma membrane
Homologues: Paralogues in human: IGHV3-64 (91% identical), IGHV3-23 (91% identical), IGHV3-74 (86% identical), IGHV3-43 (85% identical), IGHV3-53 (85% identical), IGHV3-66 (85% identical), IGHV3OR16-10 (85% identical), IGHV3OR16-13 (84% identical), IGHV3-30 (83% identical), IGHV3-48 (83% identical), IGHV3-21 (81% identical), IGHV3-33 (81% identical), and 65 more.